STAT3 (signal transducer and activator of transcription 3)
Diseases named in the same sentence as STAT3 in open-access papers (continued):
Sharing a sentence is not in itself a finding about the gene and the disease.
glioblastoma (continued). "Moreover, TAM-derived TGFBI promotes glioblastoma growth through integrin αvβ5-Src-Stat3 signaling." (PMID 38297161, 2024). "The phosphorylated-EZH2 complex targets crucial nonhistone substrates, for example, S21 phosphorylation of EZH2 enhances EZH2-mediated STAT3 methylation due to a stronger interaction with STAT3 in glioblastoma multiforme (GBM) stem-like cells." (PMID 39769907, 2024). "In GBM, uncontrolled activation of STAT3 has been observed which is related to glioblastoma growth, development, and a dismal prognosis." (PMID 39153914, 2024). "Moreover, CDK5RAP3 knockdown could efficiently reverse TSPAN6-induced STAT3 activation in glioblastoma cells." (PMID 38725860, 2024). "Since the expression of STAT3 in primary cultures and matched cryopreserved tumor samples did not reflect the original observations, we have attempted to study it upon experimental conditions of its genetic deletion in a stabilized model glioblastoma cell line." (PMID 38654280, 2024). "In addition, STAT3 expression in glioblastoma should be proven by in vivo studies." (PMID 39459502, 2024). "Thus, glioblastoma cells overexpressing TSPAN6 may induce STAT3 activation of vascular endothelial cells and promote angiogenesis in TME of glioblastoma." (PMID 38725860, 2024). "In addition, the phosphorylation of STAT3 increases in MGMT-overexpressed glioblastoma cells." (PMID 38264122, 2023). "A pro‐GBM mechanism in which CYP2E1‐PPARγ‐STAT‐1/NF‐κB/STAT‐3/STAT‐6 axis fueled tumorigenesis by reprogramming M/Mφ and a newly developed CYP2E1 inhibitor, Q11, as a promising anti‐inflammatory agent for glioblastoma treatment is uncovered." (PMID 37283464, 2023). "STAT3 has been observed in glioblastoma multiforme (GBM), and STAT3 activation is correlated with a poor prognosis in GBM." (PMID 37998723, 2023). "Meanwhile, IRF7 mediates STAT3 expression and promotes the survival and stem cell differentiation potential of glioblastoma multiforme (GBM) cells through the IL-6-STAT3 signaling pathway, and then enhances the progression and invasion of GBM." (PMID 37251373, 2023). "Additionally, STAT3 inhibition could sensitize glioblastoma to temozolomide, thus STAT3 is greatly required for elucidating mechanisms of temozolomide resistance." (PMID 37308741, 2023). "EGFRvIII/STAT3 pathway is critical signaling downstream in glioblastoma and gets involved in GBM cell proliferation, migration and progression." (PMID 36010960, 2022). "In addition, they provided evidence that monocytes take up exosomes secreted by glioblastoma cells that release signal transducer and activator of transcription 3 (STAT3) which induces expression of PD-L1 and polarization of the macrophages to the M2 tumor-supportive phenotype." (PMID 35052830, 2022). "Mechanistically, abnormal HA accumulation could bind to CD44 receptor on macrophages surface, which could regulate downstream STAT1 and STAT3 pathways in macrophages, further leading to the glioblastoma immunosuppressive microenvironment formation and ultimately promoting glioblastoma progression." (PMID 35410993, 2022). "The results of the present study demonstrate that vitexin inhibits the proliferation and invasion and induces the apoptosis of glioblastoma U251 cells through suppressing the JAK/STAT3 signaling pathway, and vitexin may be a promising potential agent for the chemotherapy of glioblastoma." (PMID 35281458, 2022). "Here, SH2 domain‐containing adapter protein F (SHF) is identified as a tumor suppressor in glioblastoma Multiforme (GBM) and its negative regulation of STAT3 activity is characterized." (PMID 35843865, 2022). "CK2 is essential for the phosphorylation and activation of STAT3, thereby contributing to the survival of glioblastoma (GBM) cells." (PMID 36009534, 2022). "In particular, different reports have provided proofs of a correlation between the staining for STAT3 in human tumor specimens and the recurrence of glioblastoma multiforme (GBM)." (PMID 34141616, 2021).
glioblastoma (continued). "It has been shown that inhibition of STAT3 in glioblastoma stem cells (GBM-SC) can promote the levels of histone H3K27 demethylation and the expression of neural-specific genes, such as FGF21, GDF15, and Myt1." (PMID 34217316, 2021). "STAT3 promotes glioblastoma stem-like properties and is a critical mediator of resistance to irradiation Based on enrichment analysis, we reasoned that overexpression of miR-671-5p could sensitize cells to radiotherapy by reducing the cell recovery ability of STAT3." (PMID 35052701, 2021). "Interestingly, although nuclear p-STAT3 was involved in EZH2 transactivating action, p-STAT3 as well as STAT3 were not methylated in PDAC, which is different from other cancer cell types that methylated STAT3 by EZH2 is involved in tumorigenesis of glioblastoma stem-like cells." (PMID 34771469, 2021). "Therefore, it strongly suggests that STAT3 inhibitors may be a valuable strategy for treating glioblastoma by eliminating GSCs." (PMID 32183406, 2020). "Signal transducer and activator of transcription 3 (STAT3) has been shown previously to be a key signaling protein driving major hallmarks of cancer, including proliferation and cell survival, and to represent a promising target for the development of targeted glioblastoma therapies." (PMID 32967361, 2020). "Therefore, we investigated whether ODZ10117 may affect STAT3 activation in glioblastoma and primary glioblastoma cells." (PMID 32183406, 2020). "Interestingly, upregulation of adenosine monophosphate-associated protein kinase (AMPK) following metformin administration abrogates the leptin-induced growth and migration of glioblastoma cells, also mediated by downregulation of STAT3 and Akt/PKB serine threonine kinase." (PMID 33316976, 2020). "For example, it was reported that glioblastoma stem cell-derived exosomes direct monocytes toward the immune suppressive “M2” phenotype, through the signal transducer and activator of transcription-3 (STAT3) pathway, creating an immunosuppressive microenvironment." (PMID 32317966, 2020). "Additionally, BMX knockdown could block the STAT3 activation, while inhibiting the glioblastoma stem cell transcription factors to disrupt the tumorigenicity of glioblastoma stem cells." (PMID 31130822, 2019). "A study in glioblastoma (GBM) cells suggests that TRIM59 promotes GBM tumorigenesis through interaction with nuclear STAT3 and maintains its transcriptional activation by preventing its dephosphorylation." (PMID 31820796, 2019). "In addition, a strong link between IL-6-STAT3 signaling and O6-methylguanine DNA methyl transferase expression and methylation and to temozolomide sensitivity in glioblastoma was found, suggesting a possible combination therapeutic approach based on IL-6/STAT3 inhibitors." (PMID 31247937, 2019). "STAT3 is constitutively activated in a variety of cancers including adult high grade gliomas (aHGGs) such as glioblastoma (GBM), and pediatric high grade gliomas (pHGG)." (PMID 31361777, 2019). "Therefore, the JAK2/STAT3 may represent a potentially important target for therapy of EGFRvIII-positive glioblastoma." (PMID 30279357, 2018). "Similarly, glioblastoma cells exposed to IL-20 demonstrate phosphorylation of STAT3, ERK and Akt." (PMID 30542269, 2018). "Moreover, BMX has also been identified as an activator of STAT3 in glioblastoma stem cells." (PMID 28514765, 2017). "In glioblastoma mutiforme (GBM) cells, Shp2 promotes EGFR and c-Met co-inhibition induced GBM cell death by inhibition of Stat3 activity." (PMID 28085101, 2017). "Aberrant EGFR signaling in GBM mediates STAT3 transcriptional activation to promote tumorigenesis, progression and invasion of glioblastoma." (PMID 29129908, 2017). "Finally, we examined whether STAT3 repression of Jmjd3 was specific to glioblastoma stem cells, or whether the STAT3 inhibition phenotype is recapitulated in normal human neural stem cells." (PMID 28384648, 2017).
glioblastoma (continued). "High levels of STAT3 activity have been found to predict intrinsic chemotherapy resistance and STAT3 inhibition allows glioblastoma cells to overcome temozolomide resistance which is a significant finding given that temozolomide is a first-line treatment for glioblastoma." (PMID 28877265, 2017). "STAT3 has already been shown to be persistently activated in a variety of cancers, and is believed to regulate multiple cancer stem cell populations including those that may drive primary brain tumors such as glioblastoma." (PMID 26314961, 2015). "Therefore, Ad-GSCs and Sp-GSCs produced histologically identical tumors with different gene expression patterns, and a STAT3/ANGPTL4 pathway is identified in glioblastoma that may serve as a target for therapeutic intervention." (PMID 25955030, 2015). "It was reported that STAT3 had functional activities in PI3K-driven oncogenic transformation and there was a crosstalk between STAT3 and PI3K signaling pathways in driving the transformation of murine glioblastoma and lymphoblastic B-cell lymphomas, and caused drug resistance." (PMID 25422792, 2014). "Importantly, STAT3 is now known to regulate growth and self-renewal of glioblastoma stem cells." (PMID 24386318, 2013). "The highest levels of leptin and ObR were found in glioblastoma multiforme (GBM), where both proteins were coexpressed with activated forms of serine/threonine protein kinase B (Akt) and signal transducer and activator of transcription 3 (STAT3)." (PMID 21771332, 2011). "Our data further reveals that ICI-resistant human glioblastomas are enriched in genes that induce IL-6, such as LGALS3, and downstream targets of the IL-6 signaling cascade such as p-STAT3, p-AKT, p-ERK1/2, and ANXA113,28,29." (PMID 40161763, 2025). "This, in turn, sensitized glioblastoma cells to TMZ, suggesting that targeting the STAT3 pathway in GAMs can mitigate exosome-mediated chemoresistance." (PMID 41502528, 2025). "The functional matrix highlighted multifunctional hubs such as STAT3, TGFB1, and PRMT5, bridging several biological processes central to glioblastoma pathogenesis." (PMID 41179304, 2025). "HHT treatment of GBM can inactivate STAT3 signaling by inhibiting PDGFRα phosphorylation and PDGFRα/Ras homolog family member A (RhoA)/Rho-associated coiled-coil-containing protein kinase (ROCK) axis to reduce glioblastoma cell proliferation, cytoskeletal remodeling, and migration." (PMID 39949739, 2025). "TAM-derived legumain exerts dual regulatory roles in glioblastoma (GBM) by promoting macrophage infiltration in an autocrine manner via the GSK3β/STAT3 pathway, while in a paracrine fashion, TAM-secreted legumain drives GBM cell proliferation and survival through integrin αv/AKT/p65 signaling." (PMID 41417432, 2025). "Both STAT3 and HIF-1α play critical regulatory roles in maintaining the M2 immunosuppressive phenotype of TAMs and contribute to immune evasion in glioblastoma." (PMID 41002423, 2025). "As shown in glioblastoma cells, ADAM8 mediates angiogenesis by inducing the expression of osteopontin (SPP1) via signal transducer and activator of transcription 3 (STAT3) signaling." (PMID 39412616, 2025). "In glioblastoma (GBM) stem cells, palmitoylation Glycogen synthase kinase 3β (GSK3β) at Cys14 mediated by ZDHHC4 can activate STAT3 signaling to improve the stemness of temozolomide (TMZ)-resistant GBM." (PMID 39877903, 2025). "Other researchers have contributed to this topic by examining the role of pacritinib, a STAT3 inhibitor, in overcoming TMZ resistance in glioblastoma." (PMID 41502528, 2025). "Enhanced S1P signalling promotes glioblastoma cell proliferation and survival by activating kinases such as AKT and CHK1, as well as transcription factors such as cMYC and STAT3." (PMID 41194660, 2025).
glioblastoma (continued). "In contrast, in renal carcinoma, pancreatic adenocarcinoma, and glioblastoma, GBP2 overexpression promotes malignancy, often by facilitating immune evasion or Stat3-driven invasion, leading to a poorer prognosis." (PMID 40564939, 2025). "Phosphorylation of EZH2 at serine 21 was found to be highly expressed in stem-like cells of glioblastoma multiforme, and this phosphorylation by protein kinase B (AKT) signaling facilitates STAT3 methylation by EZH2, thus enhancing STAT3 activity." (PMID 40028035, 2025). "Meanwhile, TSPAN6 and STAT3 were both mostly overexpressed in endothelial cells of glioblastoma, and the colocalization of TSPAN6 and STAT3 was verified in endothelial cells by single cell sequencing." (PMID 38725860, 2024). "The functional annotation analyses of predicted DE miRNA target genes showed their primary involvement in the STAT3 and HIF-1 signalling pathways and the signalling pathway of pluripotency of stem cells and glioblastoma-related pathways." (PMID 38455766, 2024). "For instance, in glioblastoma stem cells (GSCs), HEY1 is upregulated by the STAT3/NF‐κB signaling pathway, which is constitutively activated in these cells." (PMID 38351531, 2024). "For example, arsenic trioxide (ATO) can decrease the phosphorylation and activation of STAT3 and AKT through the Notch pathway, thereby reducing the proliferation of glioblastoma cells." (PMID 38672496, 2024). "In glioblastoma, it has been shown to suppress cell proliferation by modulating the PI3K/Akt and JAK/STAT3 pathways." (PMID 39769099, 2024). "In glioblastoma cells, KMT6A/EZH2 trimethylates STAT3 on K180 (STAT3K180me3) playing again a positive role in the STAT3-dependent transcriptional response and supporting STAT3Y705p." (PMID 39680066, 2024). "This study demonstrated that TSPAN6 enhanced the phosphorylation of STAT3 in glioblastoma cells, CDK5RAP3 knockdown reversed TSPAN6-activated STAT3, indicating that TSPAN6 activated STAT3 via CDK5RAP3 in glioblastoma cells." (PMID 38725860, 2024). "In glioblastoma (GBM), hypoxia enhances CSCs-mediated immunosuppression by activating the STAT3 pathway and hypoxia-inducible factor-1 alpha (HIF-1α) and hindering T-cell activation." (PMID 38704599, 2024). "Efficient STAT3 gene editing downregulated VEGF, IL‐6, and IL‐10 to reprogram disordered vasculature and the immunosuppressive microenvironment for glioblastoma therapy." (PMID 38923275, 2024). "In NSCLC and glioblastoma, anlotinib played an anticancer role by inducing apoptosis and autophagy through the JAK2/STAT3 pathway." (PMID 39508048, 2024). "In glioblastoma cells with functional PTEN, AKT is directly inhibited by PTEN with the suppression of STAT3 activation via the FOXO3/LIFRβ gene." (PMID 38339245, 2024). "In subsequent experiments, we confirmed that SRPK1 can participate in the malignant progression of glioblastoma by regulating the Wnt/β-catenin and JAK-2/STAT-3 pathways." (PMID 38397980, 2024). "Together, these findings suggest that YAP1 and STAT3 transcriptional co-activators contribute to LDHA/lactate–ERK axis-dependent CCL2 and CCL7 expression in glioblastoma cells." (PMID 38443336, 2024). "Mechanistically, LDHA-lactate-directed ERK pathway activates YAP1 and STAT3 transcriptional co-activators to upregulate CCL2 and CCL7 in glioblastoma cells, which promote macrophage infiltration into the TME." (PMID 38443336, 2024). "This validation confirmed that STAT3 was a therapeutic target for BY4003 and BY4008 in glioblastoma." (PMID 39153914, 2024). "Mechanistically, TSPAN6 enhanced the malignant progression of glioblastoma by interacting with CDK5RAP3 and regulating STAT3 signaling pathway." (PMID 38725860, 2024). "BAG3 depletion was also associated with decreases in the nuclear levels of phosphorylated (activated) STAT3, whereas ectopic STAT3 overexpression normalized BAG3 levels and function in the glioblastoma cells in which BAG3 had been knocked out." (PMID 36980278, 2023).
glioblastoma (continued). "Lastly, in glioblastoma stem cells having a sphere-like phenotype, BAG3 depletion decreased sphere-forming activity, SOX-2 expression, and the expression of STAT3, a master regulator of stemness." (PMID 36980278, 2023). "We elucidated that 5-DMN promoted G0/G1 phase arrest and apoptosis in glioblastoma cells by restraining the ERK1/2, AKT and STAT3 signaling pathways." (PMID 37139163, 2023). "Given that EGCG was previously documented to alter the Src/Janus kinase (JAK)/STAT3 pathway, as well as EMT in glioblastoma, the contribution of STAT3 was next assessed." (PMID 37189618, 2023). "As a secretory protein, C-E-Cad interacts with EGFR CR2 domain and activates STAT3, PI3K–AKT, and MAPK–ERK pathways in glioblastoma CSCs." (PMID 38933287, 2023). "EGFR (epidermal growth factor receptor)-STAT3 signaling is a fundamental pathway in tumorigenesis and propagation, and hyperactivation of EGFR is observed in 50% of glioblastoma." (PMID 38933287, 2023). "BAG-3 may be particularly interesting to investigate given that BAG-3 physically interacts with signal transducer and activator of transcription 3 (STAT3) to stabilize STAT3 and endow some stem-like qualities in glioblastoma multiforme (GBM) cells." (PMID 37970210, 2023). "Verbascoside is proven to inhibit glioblastoma-cell proliferation, migration, and invasion through upregulation of SHP-1 and inhibition of STAT3 phosphorylation." (PMID 37298405, 2023). "In human glioblastoma, Lnc-TALC promotes c-Met expression and thus Stat3 phosphorylation by competitively binding to miR-20b-3p, which is associated with temozolomide resistance." (PMID 38001489, 2023). "In glioblastoma, nuclear IGFBP2 leads to aberrant EGFR and STAT3 signaling in vitro, and RCAS-mediated IGFBP2 expression increased glioblastoma formation and progression in vivo in a mouse model, which was reversed when IGFBP2 expression was inactivated." (PMID 37029430, 2023). "It is reported that reduced PIAS3 in glioblastoma tissues promotes tumor-cell proliferation, and PIAS3 overexpression inhibits glioblastoma-cell growth by reducing STAT3." (PMID 37298405, 2023). "Specifically, while MEFV and STAT3 expression was detected in both glioblastoma cells and immune cells, SARM1 expression level was higher in NPC-like and OPC-like glioblastoma cells than in MES-like, AC-like glioblastoma cells, and other tumor cells." (PMID 35990696, 2022). "According to a study, cucurbitacin I markedly decreased p-JAK1, p-JAK2, p-STAT3, and p-STAT5 levels and inhibited proliferation of glioblastoma cells." (PMID 36193062, 2022). "The interactions of tumor cells, reactive astrocytes, and microglia in glioblastoma lead to high-level expression of TGF-β and IL-10, which promote a positive feedback loop for STAT3 signaling and generate an immunosuppressive cytokine milieu." (PMID 36193062, 2022). "Similar to that seen in glioblastoma, GC-derived EVs transport high-mobility group box-1 (HMGB1) activates signal transducer and activator of transcription 3 (STAT3) and elevates the expression of PD-L1 in neutrophils, thereby inhibiting T-cell immunity." (PMID 35090497, 2022). "Previous studies show that STAT3, as a transcription factor, promotes the expression of BNIP3 in concanavalin a-induced hepatitis and glioblastoma cells." (PMID 36207761, 2022). "The nanoRNP conjugated with single guide RNAs (sgRNAs) specifically targeted and disrupted STAT3 and RUNX1 expression, thereby inhibiting the heterogenous tumor populations in glioblastoma U87MG cells and in a xenograft model." (PMID 36153528, 2022). "While resistance to Kif11 inhibitors in other cell types is due to mechanisms that prevent these drugs from disrupting mitosis, we find that in glioblastoma (GBM), resistance to the Kif11 inhibitor ispinesib works instead through suppression of apoptosis driven by activation of STAT3." (PMID 35732128, 2022).